VIM (vimentin)
Diseases named in the same sentence as VIM in open-access papers (continued):
Sharing a sentence is not in itself a finding about the gene and the disease.
tumor (continued). "EMT is considered a key factor in tumor invasion and metastasis, and it is characterized by the absence of epithelial cell markers (e.g. cytokeratins and E-cadherin) and upregulation of the expression of mesenchymal cell markers (e.g. N-cadherin, Vimentin and Snail, Twist)." (PMID 41367628, 2025). "During EMT in tumor cells, the expression of proteins that promote cell-cell adhesion, such as E-cadherin, is decreased, while the expression of mesenchymal markers, including vimentin, MMP-2, and MMP-9, is increased, thereby enhancing cell migration and invasion capabilities." (PMID 41194934, 2025). "Strong positive correlations of vimentin in multiple tumor regions validate its utility as a well-established mesenchymal marker in response to the EMT course, confirming that it may serve as an ideal predictor for activation or completion stage in an oncogenic context in TNBC." (PMID 39371729, 2024). "Notably, vimentin is increased in metastases and circulating tumour cells relative to primary well-differentiated tumours, suggesting that exploring the mechanistic interplay with the endosome-lysosome system could reveal selective therapeutic targets." (PMID 39796673, 2024). "To verify whether SECTM1 was involved in the EMT process in vivo, we performed immunofluorescence staining for EMT markers (E-cadherin: green, Vimentin: red) on brain-frozen sections of in situ tumor-bearing mice and tumor tissue frozen sections of subcutaneous tumor-bearing mice, respectively." (PMID 38164182, 2024). "As seventy percent of metastatic CRC samples were positive for phosphorylated vimentin, peptide-reactive CD4 T-cells recognized phosphorylated vimentin-positive tumor cells directly or indirectly, and phosphorylated vimentin could become a helper peptide vaccine to treat CRC." (PMID 38339403, 2024). "Hence, we aimed to evaluate if quantifiable parameters could be established for the expression of CD44, EGFR, vimentin, and E-cadherin in terms of predicting tumor aggressiveness and prognostic significance, if any, in OSCC." (PMID 39050298, 2024). "Interestingly, in both CRC and PDAC samples, we identified hybrid subpopulations that were conserved across the tumor tissue and the peripheral blood, which were both driven by vimentin and αSMA expression, including T3, and B3 in the CRC samples and T6 and B2 in the PDAC samples." (PMID 38538742, 2024). "Furthermore, immunohistochemistry and Western blot analyses indicated that propranolol inhibited EMT in vivo, as evidenced by the upregulation of E-cadherin and downregulation of vimentin in tumor tissue (implantation site) in the propranolol group compared to the control group." (PMID 38294713, 2024). "When tumor cells invade and metastasize, they tend to lose polarity and epithelial characteristics, such as changes in the expression of proteins like E-cadherin, N-cadherin, and Vimentin, and acquire mesenchymal phenotypes similar to the enhancement of MMP expression." (PMID 38684944, 2024). "The cells described in our study also showed intracellular expression of vimentin, which is not only a specific type III intermediate filament protein typical for mesenchymal origin but also exists as a marker of highly metastatic cancers and tumour-associated stroma." (PMID 38342891, 2024). "As our GSEA shows that transcriptional level of EMT in vimentin-expressing cancer cells was opposed by IFNα response, vimentin-expressing cancer cells could evade cytotoxic IFNα response and exert higher fitness in the patient, particularly in an inflammatory tumor microenvironment." (PMID 39461475, 2024). "In addition, we verified common tumor-associated protein markers and found that after the knockdown of AGPAT5, their VEGF levels were significantly reduced, along with a significant trend of Vimentin reduction." (PMID 36845084, 2023). "Thus, in KPV+/+ cells, vimentin promotes tumor growth by conferring protection against ferroptosis." (PMID 37161053, 2023).
tumor (continued). "Our data indicate that glial cell-derived factors induce the transcriptional and translational process of EMT in tumor cells, and we confirmed this by measurement of key markers of this process such as downregulation of E-cadherin, as well as upregulation of N-cadherin and vimentin." (PMID 37572121, 2023). "The EMT marker, Vimentin, may also influence tumor progression." (PMID 36969045, 2023). "In addition, in thyroid cancer B-CPAP cells, Naringin regulates PERK/eIF2 α/ATF4/CHOP axis can upregulate the expression of E-cadherin and downregulate the expression of N-cadherin and Vimentin, which can significantly inhibit tumor cell metastasis and invasion." (PMID 37663256, 2023). "This morphological and functional shift, suggestive of the acquisition of a more aggressive tumor cell phenotype, has been associated in our experimental model with changes in the expression level of classic EMT markers, such as loss of epithelial E-cadherin and upregulation of mesenchymal Vimentin." (PMID 37048121, 2023). "Considering the critical role of the EMT process in tumor metastasis, we examined the expression of epithelial markers (E-cadherin and claudin-1) and mesenchymal markers (N-cadherin and vimentin) to address whether DDX17 is required for the EMT progression of CRC." (PMID 36593242, 2023). "Therefore, we overexpressed vimentin and vimentin‐K104Ac in the A549 and H1299 cell lines and found that the upregulation of vimentin and vimentin‐K104Ac facilitated invasion, migration, clonal formation, and tumor sphere formation." (PMID 37424170, 2023). "In CRC, vimentin expression in CAFs may reflect the higher malignant potential of the tumor." (PMID 37143134, 2023). "Given that TGFβ, Twist, and Vimentin also contribute to the generation of CSCs, drug resistance, and tumor progression 41,42, and because NDRG1 promotes chemoresistance 43, we explored whether TGFβ-driven NDRG1 could have a role on TNBC progression by modulation of CSCs." (PMID 36594086, 2023). "Vimentin is a cytoskeletal intermediate filament protein, which is mainly expressed in mesenchymal origin tissues and the cytoplasm of mesenchymal tumor cells, and plays an important role in epithelial cell development, incision healing and tumor invasion and metastasis." (PMID 38130825, 2023). "Thus, to the best of our knowledge, this is the first study characterizing the “Vimentin switch” occurring in urothelial carcinogenesis, also demonstrating its biological relevance concerning migratory capabilities of neoplastic cells and tumor formation." (PMID 36594099, 2023). "Moreover, vimentin expression was high, whereas E-cadherin expression was low in tumor buds." (PMID 35860042, 2022). "Furthermore, the expression of N-cadherin and vimentin decreased in the LV-FTO tumours." (PMID 36358640, 2022). "Thus, cynaroside could disrupt the interaction between LIPG and vimentin and subsequently reduced tumor cell invasion." (PMID 35954428, 2022). "Moreover, E-cadherin, N-cadherin, and vimentin also play important roles in tumor cells." (PMID 35571491, 2022). "In line with in vitro study, the expression of E-cadherin and Smad7 was dramatically increased and that of Ki-67, N-cadherin and Vimentin was significantly decreased in the xenograft tumor with overexpression of circFGGY, which could be rescued by miR-545-3p agomir." (PMID 35592246, 2022). "Furthermore, knocking out vimentin attenuates tumor cell invasion." (PMID 36568154, 2022). "Vimentin also plays a relevant role in the mechanotransduction of signals from the exterior of the cell to its core, as well as in the epithelial-to-mesenchymal transition (EMT) reprogramming, which is associated with the acquisition of a migratory and invasive tumor cell phenotype." (PMID 35269626, 2022).
tumor (continued). "EMT was critical for tumor cell migration, invasion, and tumor metastasis; our results showed that icaritin significantly decreased the expression of mesenchymal markers (including N-cadherin and vimentin) and increased expression of epithelial marker E-cadherin in both the A2780s and A2780cp cells." (PMID 35433438, 2022). "Moreover, vimentin expression was high and E-cadherin expression was low in tumor buds." (PMID 35860042, 2022). "Our results indicated that Vimentin and E-cadherin might be potential targets for tumor therapy." (PMID 35281866, 2022). "Vimentin gene expression was found to be strongly positively correlated with focal adhesion and extracellular matrix (ECM) turnover, hallmark processes in the tumor microenvironment during tumor angiogenesis, as well as with other described tumor endothelial markers, e.g., galectin-1 8,11,16." (PMID 35606362, 2022). "In addition, tumor‐specific Hsp90β, vimentin, and MYH9 are screened as the targets of TAPC‐4." (PMID 36031401, 2022). "Furthermore, the expression of proteins associated with tumor cell metastasis, including MMP7, MMP9, N-cadherin, vimentin and Snail, was significantly reduced, and the corresponding expression of proteins related to tumor cell apoptosis, such as caspase-3, PPAR and GSK-3β, was strongly increased." (PMID 35348430, 2022). "A more detailed analysis of the tumor tissues shows that following anti-vimentin antibody treatment of the mice, tumor vascular integrity is impaired, resulting in the less pronounced demarcation of blood vessels and dispersion of erythrocytes into the tumor parenchyma." (PMID 35606362, 2022). "However, the general increase in CD3+ T cells after TRXtr-Vim vaccination, leads to the hypothesis that both subsets are enriched in the tumor microenvironment after vimentin vaccination." (PMID 35681575, 2022). "Moreover, tumor hybrids lost their epithelial morphology and assumed a fibroblast-like appearance, which was accompanied by downregulation of E-cadherin and pan-cytokeratin, and upregulation of vimentin, α-smooth muscle actin, and fibronectin." (PMID 35562905, 2022). "In addition, EMT is a key process in tumor metastasis and is characterized by decreased expression of intercellular adhesion molecules such as E-cadherin and increased expression of mesenchymal proteins such as vimentin." (PMID 36118088, 2022). "However, the correlation between vimentin and tumor progression remained controversial." (PMID 36032170, 2022). "In addition, myeloid cells, stained for Cd11b, appeared to remain confined to the tumor periphery in untreated mice, whereas upon anti-vimentin antibody treatment Cd11b cells could be observed in the tumor core as well." (PMID 35606362, 2022). "Therefore, we performed IHC staining for the fibroblast marker vimentin on tumor tissue sections." (PMID 35842424, 2022). "Western blot assays showed that hnRNPA1 depletion inhibited the expression of E-cadherin and promoted the expression of N-cadherin and Vimentin, which suggested that hnRNPA1 might promote tumor metastasis by accelerating the transition of mesenchymal phenotypic in NSCLC." (PMID 35814393, 2022). "Our results showed that in tumour tissues and G401 cells, the expression levels of the epithelial markers E-cadherin and ZO-1 were decreased, while the expression levels of the mesenchymal markers vimentin, α-SMA, and N-cadherin were increased, indicating EMT in MRTK." (PMID 36408277, 2022). "Such a result may be explained by the fact that MSCs play a supporting role in tumorigenesis through the secretion of factors such as IL6, IL8, VEGF, platelet-derived growth factor (PDGF), fibroblast growth factor (FGF)-7, TGF-β, and vimentin, supporting the growth and chemoresistance of the tumor." (PMID 36354566, 2022).
tumor (continued). "The roles of vimentin in inter-cellular communication have been largely unexplored, however, interaction between cancer and normal cells are the keys for the establishment of tumor microenvironment (TME) and tumor metastasis where exosomes are the critical mediators." (PMID 34305581, 2021). "In addition, to confirm that HK2 can regulate EMT in CRC, we performed IHC staining to detect TJP1, E‐cadherin, vimentin and Twist1 expression in the tumour tissues of CRC patient samples, and the immunohistochemical staining of these proteins exhibited different degrees of positivity." (PMID 34378321, 2021). "The observed increases in mRNA transcripts of the mesenchymal markers vimentin and β -catenin, decreased transcripts of the cell adhesion markers E-cadherin and P-cadherin and loss of differentiation markers CDX2, CK6, CK7 and CK13 are hallmarks of transition to a mesenchymal phenotype tumour cells." (PMID 33906633, 2021). "Moreover, the risk of tumor metastasis could then be reduced by downregulating the expression of TGF-β and Vimentin due to the AMPK phosphorylation." (PMID 34794446, 2021). "Interestingly, tumor clusters could be seen to co-express pan-cytokeratin and vimentin, and large vimentin positive cells with epithelial shape in areas of tumor invasion can also be seen to co-express Ki-67." (PMID 34572115, 2021). "In cancer cells, Ser39 phosphorylation by protein kinase B (AKT/PKB) protects vimentin from proteolysis and enhances tumor growth and metastasis by altering filament assembly, which regulates cortex plasticity and could underlie the fact that cancer cells are overall softer than non-cancer cells." (PMID 36046434, 2021). "Furthermore, KIF11 knockdown significantly reduced tumor size and weight, which might be due to downregulation of N-cadherin and vimentin as well as reductions in ERK, AMPK, AKT, and CREB phosphorylation." (PMID 33968780, 2021). "Notably, all of the suppressive effects of circNR3C2 on tumor progression could be reversed by re-expression of Vimentin." (PMID 33530981, 2021). "In addition, streaks of vimentin+ cells were seen to separate CK8/18+ tumor cell nests." (PMID 34290694, 2021). "In vitro studies revealed that silencing CDCA3 could impair the migration ability of tumor cells via down-regulating EMT-related proteins such as MMP9 and Vimentin and inhibit tumor cell growth via arresting cells in the G1 cell cycle phase through regulating cell cycle related proteins like p21." (PMID 33980246, 2021). "Moreover, to further confirm the effect of DHX32/β-catenin pathway on HCC proliferation and EMT in vivo, we should also detect the expression of proliferation makers, such as PCNA, Cyclin D1, β-catenin expression, and EMT markers including E-cadherin and vimentin in the tumour tissues." (PMID 33729094, 2021). "Thus, tumor detection could be possible by detecting CTCs, especially vimentin-positive CTCs developed during the epithelial-mesenchymal transition (EMT) process in the early disease stage." (PMID 34640452, 2021). "In addition, the CMTM6 or vimentin level, or both, might be developed as biomarkers for the high likelihood of poor prognosis and tumour metastasis in patients with HCC." (PMID 33757532, 2021). "Consequently, vimentin has become a potential target for capturing CTCs in patients with tumor." (PMID 34134721, 2021). "Given that EMT and EndoMT are substantially involved in tumor neovascularization and that the mesenchymal molecule Vimentin is regarded as an independent prognosticator for poor survival, it is ideal to integrate Vimentin and/or EpCAM into the iFISH co-detection platform." (PMID 32599893, 2020). "Indeed, in our study, we found that migratory and invasive abilities were increased in tumour spheres, compared to parental A549 cells; expression levels of N‐cadherin, vimentin, MMP‐9 and MMP‐1 were also increased in tumour spheres, compared to parental A549 cells." (PMID 32396269, 2020).
tumor (continued). "However, the impact of vimentin on tumor microenvironment, particularly its implication with tumor-infiltrating immune cells, is unknown." (PMID 32850341, 2020). "Moreover, in HPV-positive OPSCC, HPV infection may exploit the β-catenin and vimentin pathways in the carcinogenesis process—the former in the cancer tissue itself, and the latter in the tumor stroma." (PMID 32794417, 2020). "In addition to hematoxylin and eosin (H&E) staining, tumor sections were immunostained for cytokeratin (Pan-CK), the proliferation marker, Ki-67, the epithelial marker, E-cadherin, and the mesenchymal marker, vimentin." (PMID 32131500, 2020). "Knocking down RNF144A-AS1 also significantly inhibited the EMT, a key contributor to tumor invasion and metastasis, by inducing the expression of epithelial markers (E-cadherin and ZO-1) and suppressing the expression of mesenchymal markers (N-cadherin and Vimentin)." (PMID 32047140, 2020). "In vitro studies have shown that vimentin may function as a tumor promoter." (PMID 32670437, 2020). "Notably, subcutaneous tumor tissues were subjected to IHC staining for E-cadherin and vimentin." (PMID 32908135, 2020). "Interestingly, moving from the tumor center towards the invasive front, a decreased number of cells expressing cytokeratin was observed, while scattered neoplastic cells with a prominent mesenchymal morpholgy acquired cytoplasmic vimentin expression." (PMID 33297475, 2020). "Upon closer analysis, in VIM+/+ mice, vimentin was absent from tumor cells but present in the cancer associated fibroblasts (CAFs) that surrounded the groups of cells that had broken off from the primary tumor, termed collective invasion packs." (PMID 31940801, 2020). "Furthermore, ADSC exosomes have been shown to induce the epithelial-mesenchymal transition and growth factors, such as vimentin and matrix metalloproteinases (MMPs), in tumor cells, which could partly explain the increased proliferation and invasion." (PMID 32523950, 2020). "In addition, some CTECs also expressed tumor markers such as vimentin." (PMID 32659050, 2020). "Metastatic tumor cells lose the expression of epithelial markers such as the cell adhesion molecule E-cadherin and shift towards a mesenchymal phenotype defined by the expression of mesenchymal markers, including vimentin, and the activation of EMT inducing transcription factors." (PMID 31952346, 2020). "The knockdown of Yotiao by short hairpin RNA inhibited tumor growth in mice, which was partly due to the fact that Yotiao knockdown induced an increase in the epithelial marker E-cadherin and decreased mesenchymal markers N-cadherin and vimentin, indicating that Yotiao plays a crucial role in EMT." (PMID 32028718, 2020). "Furthermore, vimentin has been proposed as a regulator agent of interaction between proteins of the cytoskeleton and cell adhesion molecules, participating in the processes of adhesion, migration, invasion and signal transduction in tumor cells." (PMID 31936364, 2020). "In addition to its well-known role in EMT, vimentin was also suggested to have another possible tumor-promoting mechanism in our study: it may induce immunosuppression via the PD-1/PD-L1 axis and inhibit CD8+ T cell function." (PMID 32850341, 2020). "Furthermore, our correlation analysis showed that high levels of TCTP and vimentin were significantly associated with tumor size and age respectively but not with other clinicopathological features." (PMID 32046740, 2020). "High vimentin expression was associated with high Fuhrman grade (P = 0.022), non-clear-cell histologic type (P = 0.020), absent of pulmonary metastasis (P = 0.021), and tumor hemorrhage/necrosis (P = 0.002)." (PMID 32850341, 2020). "Fourth, intra-tumor heterogeneity may bias our evaluation of vimentin expression." (PMID 32850341, 2020).